MARCO (macrophage receptor with collagenous structure)
Diseases named in the same sentence as MARCO in open-access papers (continued):
Sharing a sentence is not in itself a finding about the gene and the disease.
virus infection (6 papers, 2017 to 2025). "The protein encoded by MARCO is part of the innate antimicrobial immune system, and modulates inflammatory responses against virus infection." (PMID 30545297, 2018). "A recent RNA-seq analysis of alveolar macrophages revealed that the virus infection caused a reduction in the phagocytic receptor MARCO." (PMID 29114249, 2017). "It showed that IFN-γ produced in the lung after viral infection inhibited bacterial clearance through suppression of MARCO expression." (PMID 32038632, 2019). "IL-6 is known to be negative regulators of IFN-γ, in addition IFN-γ suppresses the expression of MARCO in alveolar macrophages inhibiting bacterial clearance in the lung after viral infection." (PMID 32038632, 2019). "The expression of MARCO in specific subsets of naive tissue-resident macrophages can be important for the primary sensing of naturally occurring viral infections." (PMID 28765216, 2017). "In contrast, our studies demonstrate a positive role for MARCO in the direct mediation of virus infection and triggering of antiviral responses in macrophages." (PMID 28765216, 2017). "While MARCO is known to be involved in the innate sensing of various bacteria, much less is known about its role in virus infection and antiviral defense." (PMID 28765216, 2017). "MARCO knockdown potentiated PRRSV infection, whereas its overexpression restricted virus infection in PAMs." (PMID 37078873, 2023).
COVID-19 (5 papers, 2021 to 2025). A disease caused by infection with severe acute respiratory syndrome coronavirus 2. "There was also downregulation of lipid metabolism-associated genes (FABP4, APOC1, APOE, MARCO) in COVID-19 effector CD8+Tcs." (PMID 37029220, 2023). "The PSMB8 cell trajectory highlighted a similar pattern for MARCO (macrophage receptor with collagenous structure) in M1-polarized alveolar macrophages: activation in mild COVID-19 cases and impairment in severe COVID-19 cases." (PMID 34225749, 2021). "Specifically, patterns of single-cell heterogeneity in bronchoalveolar cells highlighted an impairment in alveolar clearance mechanisms (e.g., lipid transport and catabolism, MARCO scavenger receptor for apoptotic cells) in equivalent cells of patients with severe COVID-19." (PMID 34225749, 2021). "Similarly, in the trajectory signature for alveolar macrophages from mild COVID-19 patients, CALR, MARCO and TNFSF13 followed the expression patterns of CD68 and PSMB8." (PMID 34225749, 2021).
pneumonia (5 papers, 2013 to 2020). An acute, acute and chronic, or chronic inflammation focally or diffusely affecting the lung parenchyma, caused by an infection in one or both of the lungs (by bacteria, viruses, fungi, or mycoplasma.). "For example, MARCO (macrophage receptor with collagenous structure) has been shown in murine models to be required for lung defense against pneumonia and inhaled particles." (PMID 30061609, 2018).
Sepsis (5 papers, 2013 to 2026). Sepsis is defined as life-threatening organ dysfunction caused by a dysregulated host response to infection. "The observed association of MARCO variants with sepsis is consistent with in vivo and in vitro observations that MARCO regulates pro-inflammatory cytokine production to whole bacteria and TLR ligands." (PMID 23617307, 2013). "In conclusion, our results demonstrate that AS protects CLP sepsis mice by inhibiting pro-inflammatory cytokine release and serum LPS levels, which is tightly related to enhancement of LPS internalization of macrophage via increasing the mRNA expression of scavenger receptors (SR-A, MARCO, SR-BI)." (PMID 24441569, 2014). "Only a small number of host genes were differentially expressed between the Gram-positive (HLA-B, SERPINB10, LOC105377885, CEACAM6, NIPA2) and Gram-negative (CBFA2T3, LOC107987303, MARCO) sepsis samples in our cohort." (PMID 40965975, 2025).
asthma (4 papers, 2023 to 2025). "Specifically, mixed granulocytic (>2% sputum eosinophils and >64% sputum neutrophils) asthma patients with anti-MARCO IgG antibodies had higher risk of subsequent asthma exacerbation triggered by infection." (PMID 38540714, 2024). "Since this research was initiated, sputum autoantibody responses to macrophage receptor with collagenous structure (MARCO) have recently been reported in severe asthma, challenging the criticality of eosinophils in asthma immunology." (PMID 37334358, 2023). "Autoantibodies targeting MARCO have been identified in the airways of a severe asthma subset." (PMID 39194521, 2024).
periampullary adenocarcinoma (4 papers, 2017 to 2022). An adenocarcinoma that arises from the periampullary region. "This study is, to our best knowledge, the first to investigate the prognostic role of tumour-infiltrating CD1a+, CD68+ and CD163+ and MARCO+ immune cells in periampullary adenocarcinoma, with particular reference to morphological type." (PMID 28673320, 2017). "The results from this study demonstrate that high infiltration of tolerogenic immature DCs independently predicts a shorter survival in patients with PB-type periampullary adenocarcinoma, and that high density of the MARCO+ subtype of TAMs predicts a shorter survival in patients with I-type tumours." (PMID 28673320, 2017).
adenovirus infection (3 papers, 2017 to 2018). "By enhancing adenovirus infection, MARCO contributes to efficient innate virus recognition through the cytoplasmic DNA sensor cGAS." (PMID 28765216, 2017). "We demonstrate that MARCO significantly enhances adenovirus infection and innate responses in macrophages." (PMID 28765216, 2017). "Importantly, MARCO is a scavenger receptor expressed in tissue-resident macrophages that recognizes various bacterial pathogens, and MARCO, for example, can enhance adenovirus infection." (PMID 30473680, 2018). "Using cells derived from mice, we show that adenovirus infection is significantly more efficient in MARCO-positive alveolar macrophages (AMs) and in AM-like primary macrophage lines (Max Planck Institute cells) than in MARCO-negative bone marrow-derived macrophages." (PMID 28765216, 2017).
atherosclerosis (3 papers, 2020 to 2024). A disease characterized by the build-up of fatty material and calcium deposition in the arterial wall resulting in partial or complete occlusion of the arterial lumen. "In conclusion, this study revealed that LCACs aggravated PS‐NP‐induced atherosclerosis by upregulating MARCO in ApoE−/− mice fed with HFD." (PMID 37144527, 2023). "Overall, this study indicates that LCACs aggravate PS‐NP‐induced atherosclerosis by upregulating MARCO." (PMID 37144527, 2023). "Thus, MARCO plays a crucial role in PS‐NP‐induced atherosclerosis." (PMID 37144527, 2023). "Lipid and atherosclerosis pathways were among the top statistically significant altered pathways in both TREM2+ (subcluster 0) and MARCO+ (subcluster 5) macrophages." (PMID 39867899, 2024). "ox-LDL is the initiating molecule in the process of atherosclerosis, which can be combined with macrophage scavenger receptors such as CD36, SR-A1 and SR-A2, SR-BI, MARCO, LOX-1, and PSOX to boot inflammation and promote atherosclerosis." (PMID 32733941, 2020).
autoimmune disease (3 papers, 2014 to 2026). A disorder resulting from loss of function or tissue destruction of an organ or multiple organs, arising from humoral or cellular immune responses of the individual to their own tissue constituents. "MARCO, a macrophage receptor with a collagen structure, is involved in the uptake of apoptotic cells, and the ability of macrophages to promptly clear apoptotic cells has been linked to autoimmune diseases." (PMID 36911710, 2023). "The wide range of genes, pathways and functions that are affected by MARCO in DC warrants more focused future investigation, and opens the prospect of therapeutically targeting MARCO receptor in the hope of ameliorating autoimmune disease, infections and cancer immunotherapy." (PMID 25089703, 2014).
Granuloma (3 papers, 2020 to 2025). A compact, organized collection of mature mononuclear phagocytes, which may be but is not necessarily accompanied by accessory features such as necrosis. "We observed that RNA expression of IL-7, IL17A, IL6, MARCO, IFN-γ, and IL-8 was significantly decreased in granulomas treated with α-MSH compared to the controls." (PMID 32350353, 2020). "Thereafter, we were able to show that both sarcoidosis in vitro granulomas and cutaneous lesional sarcoidosis granulomas contained increased neutral lipids and upregulated expression of genes involved in lipid/cholesterol metabolic pathways such as SREBF-1a/c or MARCO." (PMID 38353578, 2024).
lung adenocarcinoma (3 papers, 2021 to 2024). A carcinoma that arises from the lung and is characterized by the presence of malignant glandular epithelial cells. "MARCO was also identified as one of six diagnostic and prognostic biomarkers for patients with lung adenocarcinoma." (PMID 35664306, 2022). "In general, alveolar macrophages expressing MARCO are found in lung adenocarcinoma." (PMID 39639005, 2024).
prostate carcinoma (3 papers, 2015 to 2024). A carcinoma that arises from epithelial cells of the prostate gland. "Previous studies have determined that high fat diet can increase macrophage infiltration and alter polarization status in a prostate cancer model and demonstrated that lipid-loaded tumor-associated macrophages (MARCO+) support prostate tumor growth." (PMID 39867899, 2024). "We showed that HO-1 is expressed in MARCO-positive macrophages in prostate cancer (PCa) xenografts and human prostate cancers." (PMID 26418896, 2015). "We found that HO-1 was expressed in MARCO positive macrophages in established tumors and that there was a strong correlation between both HO-1 and MARCO expression in prostate cancer metastases." (PMID 26418896, 2015).
sarcoidosis (3 papers, 2020 to 2025). Sarcoidosis is a multisystemic disorder of unknown cause characterized by the formation of immune granulomas in involved organs. "Similar to NL and NXG, sarcoidosis lesional macrophages upregulated expression of the macrophage polarization marker genes MARCO, FCGR3A, NR1H3; the ECM-encoding gene FN1; the protease-encoding gene CTSS; and genes associated with inflammation, S100A8 and CHI3L1." (PMID 39989459, 2025). "MARCO is a class A scavenger receptor that is associated with lipid uptake and proinflammatory host defense to bacterial pathogens, and upregulated in sarcoidosis macrophages compared to controls." (PMID 38353578, 2024). "Although the role of MARCO in sarcoidosis has not been studied, TLRs have a known role in the pathogenesis of sarcoidosis." (PMID 32350353, 2020).
Alzheimer disease (2 papers, 2012 to 2021). A progressive, neurodegenerative disease characterized by loss of function and death of nerve cells in several areas of the brain leading to loss of cognitive function such as memory and language. "So, MARCO-positive macrophages can be considered as a therapeutic target not only in proliferative diseases, but also in infectious diseases (viral and bacterial) and neurodegenerative diseases such as Alzheimer’s disease." (PMID 34572315, 2021).
Arthritis (2 papers, 2023 to 2025). Inflammation of a joint. "Using multi-omic spatial and scRNAseq techniques, we identified dynamic changes in the cell populations and their transcriptomic profiles localized to MARCO+ peri-follicular medullary sinuses of TNF-Tg PLNs during the progression of arthritis development." (PMID 37691918, 2023). "Based on the findings of increased IgG2b+ plasma cells and iron-laden macrophages localized to the MARCO+ sinus region in Advanced PLNs, we evaluated changes in these cell populations by scRNAseq during Early and Advanced arthritis." (PMID 37691918, 2023).
breast tumor (2 papers, 2023 to 2025). "In vivo, genetic knockout or MARCO downregulation antibody significantly attenuated breast tumor progression through inhibition of MDSC and TAM and revitalization of CD8+ T cells and NK cells." (PMID 40695812, 2025). "The present study demonstrates that MARCO is expressed on MDSCs, and breast tumor-derived exosomes (TDEs) enriched with macrophage migration inhibitory factor (MIF) promote MDSC differentiation and amplify immunosuppressive activity by up-regulating MARCO." (PMID 40695812, 2025).
Cirrhosis (2 papers, 2023 to 2024). A chronic disorder of the liver in which liver tissue becomes scarred and is partially replaced by regenerative nodules and fibrotic tissue resulting in loss of liver function. "In contrast, the MARCO+ KCs were exhausted in the ACLF group, and the cell counts of KCs in the HC and cirrhosis groups were higher." (PMID 37380987, 2023). "Furthermore, two distinct populations of MARCO+ KCs are distinguished by the expression of TIMD4, with a selective reduction in MARCO+ TIMD4− KCs observed in the livers of cirrhosis patients." (PMID 39328386, 2024).
Co-Infection (2 papers, 2019 to 2025). "Taken together, these results showed that IL-6 not only affected the death of lung inflammatory cells but also improved macrophages phagocytic functions by increasing MARCO expression during co-infection." (PMID 32038632, 2019).
cryptococcal infection (2 papers, 2017 to 2022). "Thus, possible contribution of MARCO expression to long-term latency of C. neoformans infection and whether genetic variants of MARCO are associated with susceptibility to cryptococcosis in humans warrants further study." (PMID 29033946, 2017). "This is in line with other work showing that the scavenger receptor MARCO organizes and enhances antifungal activity during early cryptococcal infections." (PMID 36466930, 2022). "Our recent study showed that MARCO expression contributes to fungal containment during the innate phase of cryptococcal infection by enhancing production of pro-inflammatory cytokines and recruitment of mononuclear phagocytes to the infection sites." (PMID 29033946, 2017). "To explore the function of MARCO during the late/efferent phase of cryptococcal infection, we infected WT and MARCO−/− mice with C. neoformans strain 52D and analyzed the fungal burden at 35 days post infection (dpi)." (PMID 29033946, 2017). "Since MARCO affected extra-pulmonary C. neoformans dissemination, we next studied its effects on systemic immune responses during the efferent phase of cryptococcal infection." (PMID 29033946, 2017). "Using a murine model of cryptococcosis, we found that MARCO expression shifts both local and systemic Th responses away from protective Th1 toward non-protective Th2 response with impaired classical activation of macrophages." (PMID 29033946, 2017). "While future studies are needed to clarify this, our studies indicate that both MARCO and SR-A can promote Th2 polarization during cryptococcal infection possibly via different mechanisms." (PMID 29033946, 2017). "Macrophage receptor with collagenous structure (MARCO) contributes to fungal containment during the early/innate phase of cryptococcal infection; however, its role in adaptive antifungal immunity remains unknown." (PMID 29033946, 2017). "Thus, MARCO expression contributes to fungal growth and dissemination during the efferent phase of cryptococcal infection." (PMID 29033946, 2017). "Interestingly, our previous study demonstrated that MARCO orchestrates innate defenses and contributes to fungal containment during initial response to cryptococcal infection by promoting early inflammatory cytokine production in the lungs and phagocytosis by myeloid cells." (PMID 29033946, 2017). "Here, we demonstrated that MARCO expression ultimately promotes fungal persistence and dissemination by directly or indirectly contributing to the development of non-protective responses during cryptococcal infection." (PMID 29033946, 2017).
fibrosis (2 papers, 2022 to 2024). the formation of excess fibrous connective tissue in an organ or tissue in a reparative or reactive process. "Moreover, targeted reduction of cutaneous and pulmonary infiltration of MARCO+ inflammatory monocytes and macrophages using an innovative PLG nanoparticle strategy effectively prevented and, more importantly, reversed skin and lung pathology in a BLM-induced mouse model of fibrosis." (PMID 35104243, 2022).
fungal infection (2 papers, 2017 to 2021). "The current study demonstrates that MARCO exhibits some interesting similarities and differences during fungal infections when compared with our previous study on the role of another scavenger receptor, SR-A." (PMID 29033946, 2017). "Thus, we hypothesized that MARCO also regulates T cell-mediated immunity during fungal infections, possibly through modulation of DC migration and/or activation." (PMID 29033946, 2017).
Hypertension (2 papers, 2025). The presence of chronic increased pressure in the systemic arterial system. "Additionally, the fact that higher ACE/ACE2 ratios have been linked to hypertension and worse outcomes in Covid-19 could implicate MARCO in the susceptibility to severe disease." (PMID 41439503, 2025). "Additionally, the fact that higher ACE/ACE2 ratios have been linked to hypertension and worse outcomes in Covid-19 30 could implicate MARCO in the susceptibility to severe disease." (PMID 40093086, 2025).
lupus (2 papers, 2011 to 2019). "We found that the numbers of MARCO+ cells were significantly reduced in the spleens of lupus MRL/lpr mice." (PMID 32082297, 2019). "A previous study reported the presence of the anti-MARCO antibody in lupus-prone mice and systemic lupus erythematosus (SLE) patients." (PMID 21281474, 2011). "Since MZMs expressing MARCO are deficient in the spleens of lupus MRL/lpr mice, we further determined whether lupus IgG affects GC and plasma cells in red pulp macrophages and the MZM deficiency." (PMID 32082297, 2019).
meningitis (2 papers, 2011 to 2016). A disorder characterized by acute inflammation of the meninges of the brain and/or spinal cord. "Using a rat meningitis model, we investigated the influence of MARCO and FPRL1 on rCRAMP (rat cathelin-related antimicrobial peptide) expression after infection with bacterial supernatants of Streptococcus pneumoniae (SP) and Neisseria meningitides (NM)." (PMID 21299846, 2011). "Expression of FPRL1 and MARCO was analyzed by immunofluorescence and real-time RT-PCR in a rat meningitis model." (PMID 21299846, 2011). "Positive MARCO staining and MARCO/GFAP co-localization were also shown after 12, 22, 39 h of infection with SP, albeit weaker than in meningitis by NM." (PMID 21299846, 2011).
Obesity (2 papers, 2012 to 2018). Accumulation of substantial excess body fat. "Four SNPs located in the intronic regions of MARCO, which encodes an AT macrophage-specific marker regulated by obesity and dietary intervention, showed associations with P<10−20." (PMID 23028366, 2012).
ovarian carcinoma (2 papers, 2021). A malignant neoplasm originating from the surface ovarian epithelium. "Additional analyses are required in order to elucidate the impact of MARCO‐positive TAMs on spheroid tumor cells and whether this interaction might further influence disease progression of ovarian cancer patients." (PMID 34060699, 2021).
pneumococcal infection (2 papers, 2017 to 2018). Infections with bacteria of the species streptococcus pneumoniae. "Next, we quantified the mRNA expression of MARCO, a receptor being involved e.g. in the defence of pneumococcal infections of the lungs, where an increase was detected in both genotypes with a tendency of lower levels in CRAMP-KO microglia but not reaching statistical significance." (PMID 28915816, 2017).